RN7SL597P (RNA, 7SL, cytoplasmic 597, pseudogene)
Gene: Miscellaneous RNA gene on chromosome 13 (41,121,876 to 41,122,171, forward strand). Ensembl gene ENSG00000244264.
Homologues: Orthologues: chimpanzee Metazoa_SRP (99% identical), macaque Metazoa_SRP (94% identical), mouse Gm22649 (72% identical), rat Metazoa_SRP (69% identical). Paralogues in human: RN7SL1 (87% identical), RN7SL2 (86% identical), RN7SL3 (85% identical), RN7SL126P (83% identical), RN7SL45P (83% identical), RN7SL709P (83% identical), RN7SL664P (83% identical), RN7SL448P (83% identical), RN7SL125P (82% identical), RN7SL493P (82% identical), RN7SL566P (82% identical), RN7SL618P (82% identical), and 701 more.